RNU6-95P (RNA, U6 small nuclear 95, pseudogene)
Gene: Small nuclear RNA gene on chromosome 4 (68,003,895 to 68,004,001, forward strand). Ensembl gene ENSG00000207428.
Homologues: Orthologues: chimpanzee U6 (95% identical), macaque U6 (93% identical), dog U6 (78% identical), rabbit U6 (78% identical), pig U6 (77% identical), mouse Gm24887 (72% identical), rat LOC120098055 (69% identical), mouse Gm22663 (66% identical). Paralogues in human: RNU6-21P (87% identical), RNU6-31P (87% identical), RNU6-38P (87% identical), RNU6-1 (86% identical), RNU6-15P (86% identical), RNU6-2 (86% identical), RNU6-3P (86% identical), RNU6-40P (86% identical), RNU6-4P (86% identical), RNU6-574P (86% identical), RNU6-5P (86% identical), RNU6-6P (86% identical), and 1288 more.